NOTCH1 (notch receptor 1)
Diseases named in the same sentence as NOTCH1 in open-access papers (continued):
Sharing a sentence is not in itself a finding about the gene and the disease.
cancer (continued). "However, reports regarding PFGFRA, HRAS, AKT1, FLT3, and NOTCH1 are lacking in the TCGA tonsil cancer data." (PMID 36979829, 2023). "As reninomas do not respond to conventional anti-cancer therapies, it may be reasonable therefore, to consider NOTCH1 inhibitors in patients with otherwise incurable reninoma." (PMID 37749094, 2023). "Importantly, we found that SS at the same concentrations active in cancer cells did not affect Notch1 cleavage or expression in activated T-cells, nor did it inhibit T-cell proliferation or IL-2 secretion." (PMID 37901240, 2023). "The role and clinical relevance of Notch1 in cancers have not been well illustrated." (PMID 37859809, 2023). "Furthermore, both arecoline and arecoline N-oxide increase the expression levels of EMT inducers, such as ROS, NOTCH1, and cytokines, and decrease epigenetic protein expression, activating the EMT pathway, and ultimately leading to the development of cancer and its progression to a metastatic stage." (PMID 37190117, 2023). "In summary, macrophages could induce the activation of DLL3-dependent Notch1/Notch2 signaling, the upregulation of IL-33, and the degradation LG3BP and HSPA8, resulting in enhanced cancer-cell proliferation and elevated IL-1β, IL-12, and IL-10 secretion by macrophages." (PMID 35382168, 2022). "Since many studies have proved the oncogenic effect of Notch1 and Notch2, we collected the supernatant from the co-culture as the cell-culture-conditioned medium and measured cell proliferation using MTT assay to verify the effect of co-culture on the proliferation of cancer cells." (PMID 35382168, 2022). "Compared to Del-c1 and c3, the majority of cancer genes were deleted by DEL-c2, such as CDKN2A (207/528), FHIT (133/528), KDM6A (42/528), RB1 (27/528), FAT1 (23/528), NFE2L2 (13/528), ERBB4 (20/528), CUL3 (11/528), PTEN (9/528), ZNF750 (13/528) and NOTCH1 (8/528)." (PMID 36272974, 2022). "However, Notch1-targeted drugs against TNBC have not advanced to clinical trials due to low anti-cancer efficacy in preclinical studies." (PMID 34922602, 2021). "Six overexpressed oncogenes including BCL2, NOTCH1, SOX4, and CTNNB1 and 10 downregulated tumor suppressor genes including PRKCB, IRF1, CYLD, and TGFB1 were identified as the targets of the DE miRNAs, which may promote cancer development." (PMID 34336826, 2021). "Moreover, the reduction in stemness is not due to the reduced motility of cancer cells upon Notch1 inhibition and subsequent reduced interaction with the macrophages, as Notch1 inhibition in MDA-MB-231 cancer cells does not affect their motility." (PMID 34911937, 2021). "In addition, FEZF1-AS1 may sever as an endogenous sponge of miR-34a to up-regulate NOTCH-1 in NSCLC cells, thereby increasing the invasion and migration of cancer cells." (PMID 32349744, 2020). "In addition to Notch1, the activation of the WNT/β-catenin pathway induces EMT in cancers." (PMID 33334065, 2020). "g., transfection) of stemness genes, such as OCT3, SOX2, KLF4, MYC, NOTCH1, NANOG, and LIN28, as well as epithelial-mesenchymal transition (EMT) genes (ZEB1, SNAI, VIM, TWIST, etc.), leads to stem phenotype induction and increased stem-like cancer cell activity." (PMID 32523653, 2020). "Moreover, mutations of FBWX7, ERBB2, TET2, BCL2L1, NOTCH1, FGFR1 and TSC1 were only detected in patients without germline cancer-associated variants." (PMID 30850667, 2019).
cancer (continued). "Overall our findings indicate JMJD3 and p300 as general Notch1 and Notch3 signaling co-activators in T-ALL and suggest further investigation on the potential therapeutic anti-leukemic efficacy of their enzymatic inhibition in Notch/c-Myc axis-related cancers and diseases." (PMID 31001470, 2019). "Moreover, blockade of EP4 and Notch 1 did not alter the expression of miR-92a (data not shown), implicating that miR-92a regulated cancer cell growth through EP4/Notch 1 signaling pathway." (PMID 29849934, 2018). "Interestingly, we found a higher expression of Notch-1 mRNA and a significant positive correlation between Notch-1 & -3 and Syndecan-1 mRNA levels in carcinoma tissues of triple negative IBC vs non-IBC." (PMID 28270211, 2017). "The first evidence for the involvement of Notch in cancer was the detection of a rearrangement between the intracellular part of Notch1 (NICD1) and the T-cell receptor beta (TRB) leading to high-level expression of truncated and constitutively active Notch1 in T-ALL." (PMID 26713603, 2016). "However, mutual exclusivity between NOTCH1 and PIK3CA, which was identified as SMGs via genomic analyses of ESCC patients, has not previously been implicated in any type of cancer." (PMID 26528858, 2016). "However, Notch1 was only activated by this treatment in the T47D cancer cells and not in the non-cancer HB2 cells, and MRP1 induction was dependent on Notch1 activity only in the cancer cells." (PMID 26362310, 2015). "Additionally, 12 T cells also showed increased expression of the stemness genes Sox2, Oct4 and Nanog as well as several developmental genes known to be deregulated in cancer stem cells, such as SHH, Notch1, Gli1, and Jagged gene expression and protein expression." (PMID 26597727, 2015). "PCR amplification of genomic DNA, aimed at assessing its methylation state as shown further below, revealed the existence of a small deletion in the Notch1 promoter region of two different strains of HeLa cells, which was not present in other cancer cells like PC3 and Caski." (PMID 20442780, 2010). "Furthermore, miR-662 overexpression in MDA-MB-231 cells substantially increased mRNA expression levels of stemness markers involved in embryogenesis and cancer, such as NOTCH1, WNT7b, ZEB1, TCF3, and SNAI2, reinforcing the notion that miR-662 expression enhanced stem-like properties of BC cells." (PMID 37443350, 2023). "Given that Notch1 and TGF-β signalings play crucial roles in cancer cell migration, angiogenesis, and metastasis, we hypothesized that a combination of CUR and LUT treatment-induced growth inhibition through the regulation of Notch1 and TGF-β proteins in CL188 cells." (PMID 35740666, 2022). "However, in SCC, another necessary step in TGFβ-Notch1 induction of EMT is ZEB1-dependent inhibition of Notch3, suggesting that Notch1 and Notch3 may have different cancer-dependent roles in EMT induction and highlighting that the use of pan-Notch inhibitors may not be universally useful." (PMID 34680255, 2021). "Co-occurring of genetic mutations in cancers with KDM5C alterations were not uncommon in both early-stage and advanced stage cohort and some of them are prevalent driver genes (e.g., LRP2, KMT2C, PBRM1, NOTCH1, FAT1, SETD2, NSD1, etc.), while their clinical significance remained undetermined." (PMID 33953726, 2021). "Of note, plasma membrane NOTCH1 was uniquely associated with the ablumenal aspect of the endothelium, in direct contact with closely adherent perivascular cells that expressed the HIF-induced non-canonical NOTCH antagonist DLK1, a cancer pericyte-related antigen, together with SMA and PDGFRA." (PMID 29305721, 2018). "Since Notch-1 is important in the control of CSCs proliferation; regulation of Notch-1 could suppress CSCs proliferation and down-regulate the secretion of vascular endothelial growth factor (VEGF), thus decreased micro-vessel density and further inhibited cancer metastasis." (PMID 27338343, 2016).
cancer (continued). "In 2010, we found that Notch1-activated form and its downstream target were expressed in SOX2- and OCT4-positive cells in human NPC, suggesting that Notch1 signaling was activated in these cells and might involve in molecular regulation of cancer stem/progenitor-like cells in NPC." (PMID 23443123, 2012). "The signaling pathways involved in the activation of EMT in cancer cells exposed to NETs are not completely elucidated but several evidences indicate the involvement of β catenin, certain cytokines, TGFβ, NF-kB, Notch 1 and ITGB1-ILK axis that may act independently or synergistically." (PMID 41142788, 2025). "Non-NE cancer cells exhibited higher Notch signaling activity (i.e., high HES1 and NOTCH1/2 expression) and higher nuclear AR levels." (PMID 39024561, 2024). "Although not covered in the current investigation, cancer stem cell markers including CD133, CD44, DLK1, and Notch1 as well as the β-catenin/p-GSK3β signaling pathway were significantly down-regulated, and the self-renewal capacity of CSCs was suppressed." (PMID 39000345, 2024). "In this study, DAPT inhibited cancer growth both in vitro and in vivo, but Notch2/DLL rather than Notch1/Hes1 signaling was responsible for those effects in GH3 cells." (PMID 31508369, 2019). "Our analysis also revealed ectopic rearrangements affecting multiple known cancer genes, some of which bore the hallmarks of RAG activity (e.g., Ikzf1, Kremen1), while others lacked RSS-like motifs at breakpoint junctions (e.g., Notch1, Pten)." (PMID 31167132, 2019). "Present data show that NILCO molecules (Notch1, Notch2, Notch3, Notch4, DLL4, and JAG1) and targets (Survivin, Hey2, IL-1R tI, and OB-R) were expressed in EmCa regardless of ethnicity and cancer type." (PMID 28659656, 2017). "We characterized expression of Syndecan-1 and the CSC marker CD44, Notch-1 & -3 and EGFR in carcinoma tissues of triple negative IBC (n = 13) and non-IBC (n = 17) patients using qPCR and immunohistochemistry." (PMID 28270211, 2017). "In this study, we examined the expression of Syndecan-1 and its correlation with the CSC marker CD44, Notch-1 & -3 and EGFR expression in carcinoma tissues of triple negative IBC and non-IBC patients." (PMID 28270211, 2017). "Compared to control cells transfected with pLK 0.1-GFP shRNA, expression levels of RKIP were not affected in Notch1-knocking down cells, suggesting that RKIP is an upstream component of Notch1 signaling in these cancer cells." (PMID 26716415, 2016). "In our study, NOTCH1 was constitutively active in most NSCLC samples but less in SCLC and lacking in cancer-free tissue." (PMID 23028920, 2012). "Most slides from cancer-free tissue lacked expression of CCND1, CD44, CDH1, EGFR, ERBB2, KIT, keratins, NOTCH1, PAK1, PTGS2, SNAI1, and VIM but showed staining of MUC1, HIF1A, NKX2-1, SFTPC, and STAT3, which were also found in AdCa." (PMID 23028920, 2012). "In addition, JAG2, NOTCH1, and NOTCH3 tend to increase after anti-cancer therapy, although there is no significance." (PMID 39074091, 2024). "As oncogenic Notch1 and over-activation of IGF1 are known to promote cancer development, LUNAR1 may be active in other cancers with Notch1 alterations." (PMID 36230680, 2022). "Interestingly, two out of three TNBC samples not expressing EGFR are also Notch3 negative but express Notch1 (case 2), thus reinforcing the relevant Notch3-EGFR direct correlation in this cancer subtype." (PMID 29795369, 2018). "Taken together, our results indicate that the CJ-induced repression of mutant Notch1 re-activates the apoptotic machinery in T-ALL cells and strengthen the rationale for the use of SERCA inhibitors in the treatment of Notch1 mutant T-ALL, and probably of those cancers with mutant Notch1." (PMID 26821066, 2016).
cancer (continued). "APH1A (anterior pharynx defective 1 homolog A) and NOTCH1, also found to be frequently upregulated genes in H class tumors, are components of the NOTCH signaling pathway, which when dysregulated, participates in a number of pathologies, including cancer and non-cancerous diseases." (PMID 35565454, 2022). "However, the Notch1 protein expression was confirmed negative in the KYSE450 cells and weakly positive in the KYSE140 cells, although Notch1 RNA expressed in a similar level in these three cancer cell lines." (PMID 23409141, 2013). "The CD24neg subpopulation within CD44+CD24neg/low cells showed no Notch1 activation and was GSI insensitive both in 3D (spheres and soft agar colonies) and in xenografts, highlighting important therapeutic implications of heterogeneity in cancer stem cell populations." (PMID 23982961, 2013). "In the present study, we found that Notch1 mRNA and ICN (the intracellular domain of Notch1) expression is higher in ICC tissue than in noncancerous tissue adjacent to the cancer lesions, and all cancer cell lines expressed high levels of ICN compared with normal biliary epithelial cells." (PMID 23688168, 2013).
infection (52 papers, 2008 to 2026). The state of being infected such as from the introduction of a foreign agent such as serum, vaccine, antigenic substance or organism. "As expected, infection with Pou5f1-mCherry vector induced both Pou5f1 and Ascl1 expression in Notch1/2-deficient Müller glia." (PMID 40388211, 2025). "We report that the simultaneous induction of Notch-1 signalling and alterations to β-catenin/Wnt pathway are associated with the inhibition of goblet cell maturation and enhanced crypt cell proliferation at the peak of infection." (PMID 28323899, 2017). "The increase in VH was likely supported by increases in Col3a1 and Notch1 mRNA on 7 and 10 dpi; while the crypt elongation was reinforced by increased Ki67 mRNA following infection." (PMID 36867919, 2023). "An initial infection with the SARS-CoV2 virus resulted in the expansion of Notch4 and Notch1 Tregs, the latter favored by rare genetic variants found in the susceptible host." (PMID 36282598, 2023). "Notch1 mRNA expression was significantly downregulated after infection with lentivirus carrying anti-Notch1 shRNA." (PMID 36038820, 2022). "KEGG pathway analysis found that the Notch1 signaling pathway participated in the infection of SH-SY5Y cells by KSHV." (PMID 34717617, 2021). "According to KEGG pathway results, the Notch1 signaling pathway showed a strong correlation with infection." (PMID 34717617, 2021). "The data in this critical study demonstrated that through Notch-1/IL-6 signaling, anti-TNF-α agents decreased ACE2 expression and shedding through TMPRSS2/TACE modulation and increased the susceptibility to infection." (PMID 34025650, 2021). "Specifically, MAP infection in macrophages induced Notch-1 and IL-6 signaling and resulted in the hijacking of MCL-1 causing apoptosis and persistence infection." (PMID 33072191, 2020). "While the data strongly support the role of Notch-1 in the modulation of macrophage response during infection, it also suggests that MCL-1 is involved and should be elucidated further." (PMID 32635645, 2020). "Recently, we reported that Notch-1 signaling plays a key role in macrophage polarization and response during infection." (PMID 33072191, 2020). "We observed that the suppression of Notch-1 stimulated the apoptotic rate from 6% to 22.5% in U2OS cells after Notch-1 shRNA infection." (PMID 33411691, 2020). "Our data demonstrated that in OS cells, Notch-1 shRNA infection led to a reduction in wound closure compared with that of the control group." (PMID 33411691, 2020). "Our MTT data showed that Notch-1 shRNA infection repressed viability in both U2OS and MG63 cells at 48 hours and 72 hours." (PMID 33411691, 2020). "Semi-quantitative RT-PCR showed an up-regulation of Notch1/NICD and Notch1 target Hes5 after ad-Myc/ad-Cre infection of the cultured adult Rosa-NICD cochlea." (PMID 31797926, 2019). "In order to confirm that comparable Notch1 activation was similarly affected during in vivo infection, NICD was examined in characterized patient‐derived CIN1–3, as well as uninfected cervix." (PMID 28497579, 2017). "In this study, we have examined Notch1 disruption by E6 in productive infection and during abortive/transforming infection." (PMID 28497579, 2017). "We found that induction of HES1 and OLFM4 and the down-regulation of ATOH1 transcript levels was consistent with the increased Notch-1 signalling in crypts at the peak of infection." (PMID 28323899, 2017). "Together, these results indicate a counter-balance between the effects of infection-induced NOTCH1 and SHH signaling cascades to regulate CD4+CD25+FoxP3+ Treg expansion." (PMID 27080341, 2016). "Further, counter-regulatory roles of SHH and NOTCH1 signaling during mycobacterial-infection of human DCs was also evident." (PMID 27080341, 2016).